EZH2 (enhancer of zeste 2 polycomb repressive complex 2 subunit)
Description:
Catalytic subunit of the PRC2/EED-EZH2 complex, a Polycomb group (PcG) complex that methylates 'Lys-9' (H3K9me) and 'Lys-27' (H3K27me) of histone H3, leading to transcriptional repression of the affected target gene. Able to mono-, di- and trimethylate 'Lys-27' of histone H3 to form H3K27me1, H3K27me2 and H3K27me3, respectively. Displays a preference for substrates with less methylation, loses activity when progressively more methyl groups are incorporated into H3K27, H3K27me0 > H3K27me1 > H3K27me2. Compared to EZH1-containing complexes, it is more abundant in embryonic stem cells and plays a major role in forming H3K27me3, which is required for embryonic stem cell identity and proper differentiation. The PRC2/EED-EZH2 complex may also serve as a recruiting platform for DNA methyltransferases, thereby linking two epigenetic repression systems. Genes repressed by the PRC2/EED-EZH2 complex include HOXC8, HOXA9, MYT1, CDKN2A and retinoic acid target genes. EZH2 can also methylate non-histone proteins such as the transcription factor GATA4 and the nuclear receptor RORA. Regulates the circadian clock via histone methylation at the promoter of the circadian genes. Essential for the CRY1/2-mediated repression of the transcriptional activation of PER1/2 by the CLOCK-BMAL1 heterodimer; involved in the di and trimethylation of 'Lys-27' of histone H3 on PER1/2 promoters which is necessary for the CRY1/2 proteins to inhibit transcription (By similarity).
Synonyms: KMT6; EZH1; ENX-1; KMT6A; ENX1; EZH2b; WVS; WVS2
Tractability: Small molecule: an approved drug acts on it; a structure with a bound ligand is known; a high-quality ligand is known. PROTAC: it is named in the literature on targeted protein degradation; UniProt records ubiquitination sites on it; ubiquitination databases record sites on it; a small molecule that binds it is known.
Target class: Writer; Protein methyltransferase; Epigenetic regulator
Chemical probes: CPI-1205 (high quality), CPI-169 (high quality), CPI-360 (high quality), EI1 (high quality), EPZ005687 (high quality), EPZ011989, EPZ011989 (high quality), GSK343 (high quality), JQEZ5, PF-06821497, UNC0642 (high quality), UNC1999 (high quality), UNC6852 (high quality), tazemetostat (high quality)
Gene: Protein-coding gene on chromosome 7 (148,807,257 to 148,884,330, reverse strand). Ensembl gene ENSG00000106462.
Subcellular location: Nucleus
Subcellular location (Human Protein Atlas): Nucleoplasm
Pathways (Reactome):
Disease: Defective pyroptosis; HCMV Early Events
Gene expression (Transcription): PRC2 methylates histones and DNA; Transcriptional Regulation by E2F6
Cell-Cell communication: Negative Regulation of CDH1 Gene Transcription
Cellular responses to stimuli: Oxidative Stress Induced Senescence
Chromatin organization: PKMTs methylate histone lysines
Developmental Biology: Activation of anterior HOX genes in hindbrain development during early embryogenesis
Immune System: Regulation of PD-L1(CD274) transcription
Signal Transduction: Regulation of PTEN gene transcription
Gene Ontology:
Molecular function: chromatin binding; chromatin DNA binding; histone binding; histone H3K27 methyltransferase activity; histone H3K27 trimethyltransferase activity; histone methyltransferase activity; nucleosome binding; promoter-specific chromatin binding; protein binding; protein-lysine N-methyltransferase activity; RNA binding; transcription corepressor binding; histone H3 methyltransferase activity; transcription corepressor activity; DNA binding; lncRNA binding; primary miRNA binding; ribonucleoprotein complex binding; RNA polymerase II cis-regulatory region sequence-specific DNA binding; RNA polymerase II core promoter sequence-specific DNA binding; sequence-specific DNA binding; transcription cis-regulatory region binding
Biological process: heterochromatin formation; negative regulation of DNA-templated transcription; negative regulation of gene expression, epigenetic; negative regulation of retinoic acid receptor signaling pathway; negative regulation of transcription by RNA polymerase II; positive regulation of cell cycle G1/S phase transition; positive regulation of cell migration; positive regulation of cell population proliferation; positive regulation of epithelial to mesenchymal transition; positive regulation of GTPase activity; positive regulation of MAP kinase activity; positive regulation of protein serine/threonine kinase activity; regulation of circadian rhythm; regulatory ncRNA-mediated heterochromatin formation; subtelomeric heterochromatin formation; chromatin organization; regulation of DNA-templated transcription; B cell differentiation; cell development; chromatin remodeling; facultative heterochromatin formation; hippocampus development; negative regulation of cytokine production involved in inflammatory response; negative regulation of gene expression; positive regulation of dendrite development; and 3 more
Cellular component: chromatin; chromosome; chromosome, telomeric region; ESC/E(Z) complex; heterochromatin; nucleoplasm; nucleus; chromatin silencing complex; PcG protein complex; pericentric heterochromatin; pronucleus; synapse
Genetic constraint (gnomAD): Loss-of-function variants: 14 observed, 80.44 expected, observed/expected ratio (o/e) 0.17, 90% interval 0.11 to 0.27. The upper end of that interval is the gene's LOEUF score, 0.27, which puts it in group 1 of 6, group 1 being the genes least tolerant of losing a copy. Missense variants: 423 observed, 825.79 expected, observed/expected ratio (o/e) 0.51, 90% interval 0.47 to 0.56. Synonymous variants: 297 observed, 281.11 expected, observed/expected ratio (o/e) 1.06, 90% interval 0.96 to 1.16.
Gene-disease validity (ClinGen):
ClinGen rates the evidence that EZH2 causes each of these diseases.
Weaver syndrome (autosomal dominant): Definitive. Weaver syndrome (WVS) is a rare, multisystem disorder characterized by tall stature, a typical facial appearance (hypertelorism, retrognathia) and variable intellectual disability.
Cancer hallmarks: escaping programmed cell death (promotes); proliferative signalling (promotes); tumour promoting inflammation (suppresses); invasion and metastasis (promotes); genome instability and mutations (suppresses); escaping immune response to cancer (promotes); angiogenesis (promotes); genome instability and mutations (promotes); suppression of growth (promotes); change of cellular energetics (promotes)
Homologues: Orthologues: chimpanzee EZH2 (100% identical), dog EZH2 (99% identical), chimpanzee EZH2 (99% identical), macaque EZH2 (99% identical), guinea pig EZH2 (98% identical), pig EZH2 (98% identical), mouse Ezh2 (98% identical), rat Ezh2 (97% identical), rabbit EZH2 (97% identical), tropical clawed frog ezh2 (93% identical), zebrafish ezh2 (86% identical), Caenorhabditis elegans met-1 (14% identical), and 12 more. Paralogues in human: EZH1 (64% identical), NSD1 (22% identical), NSD3 (21% identical), NSD2 (21% identical), SETD2 (17% identical), KMT2C (15% identical), ASH1L (14% identical), KMT2D (14% identical), KMT2A (14% identical), EHMT1 (14% identical), EHMT2 (13% identical), KMT2B (13% identical), and 7 more.
Diseases named in the same sentence as EZH2 in open-access papers:
EZH2 is named in the same sentence as 641 diseases in open-access papers, as found by Europe PMC text mining. Sharing a sentence is not in itself a finding about the gene and the disease. The quoted sentences say what the papers report.
breast cancer (674 papers, 2004 to 2026). A primary or metastatic malignant neoplasm involving the breast. "EZH2 is frequently overexpressed in breast cancer, and high expression levels are strongly associated with poor prognosis." (PMID 41544165, 2026). "As in breast cancer, miR-101 loss in prostate tumors unleashes EZH2 and H3K27me3-mediated silencing across metastasis-suppressive programs in prostate cancer." (PMID 41301491, 2025). "We have previously shown that the soft matrix associated enhancer of zeste homolog 2 (EZH2) upregulation drives breast cancer cells towards more undifferentiated cell state." (PMID 40425576, 2025). "High-level expression of ITGA11 or EZH2 was associated with poor survival and a decrease in recurrence-free survival of breast cancer patients." (PMID 38664825, 2024). "While EZH2 has previously been linked to breast cancer metastasis, the participation of SMYD2 in breast cancer metastasis has been suggested but never demonstrated." (PMID 38296970, 2024). "The HM enzyme EZH2 is associated with more severe forms of BC.Recent studies have shown that HER2-amplified breast cancer shows enhanced H3 and H4 lysine acetylation." (PMID 40230896, 2024). "It is known that the overexpression or mutation of EZH2 is related to several invasive tumor types, such as prostate cancer, breast cancer and different types of lymphoma, and indicates that the prognosis of patients is poor." (PMID 38764053, 2024). "A high level of EZH2 is implicated in tumorigenesis and correlates with poor prognosis in various tumor types, including breast cancer, ovarian cancer, etc.." (PMID 38254989, 2024). "Overall, we concluded that augmented expression of EZH2 is associated to reduced expression of EZH2-target mesenchymal genes and poor survival in breast cancer patients." (PMID 39174513, 2024). "In breast cancer, comprehensive evidence indicates that EZH2 facilitates metastasis, but the underlying molecular mechanism is unclear." (PMID 39174513, 2024). "In prostate cancer, breast cancer, myeloma, and OS, high EZH2 levels are associated with tumor invasiveness and metastasis." (PMID 38886296, 2024). "The expression of EZH2 is linked to the expression of RelB, which is differentially expressed between ER-negative and ER-positive breast cancer lines." (PMID 39768352, 2024). "High levels of EZH2 are not only associated with breast cancer tumor immune response, Ezh2 also acts with Stat3 as a transcriptional activator to alter the tumor immune response in melanoma." (PMID 37853322, 2023). "The expression and subcellular localization of phosphorylated EZH2 differs HER2-positive breast cancer invasiveness in a site-specific manner, which associated with metastasis." (PMID 37803297, 2023). "Gain-of-function mutations and increased EZH2 expression have been previously identified in patients with ovarian cancer, non-small-cell lung cancer, melanoma, breast cancer, prostate cancer, pancreatic cancer, and hematologic malignancies." (PMID 38275371, 2023). "SUMOylation inhibition caused decreased EZH2 and H3K27me3 level in colorectal cancer and breast cancer." (PMID 35338347, 2023). "Overexpression and hyperactivation of enhancer of zeste homolog 2 (EZH2) have been implicated in several cancers, including lung cancer, breast cancer, prostate cancer, and hematological malignancies." (PMID 37461108, 2023). "EZH2 has been implicated to have critical role in multiple carcinogenesis and tumor development and progression, including breast cancer." (PMID 37803297, 2023). "The study found a negative correlation (r = − 0.2394, P = 0.03) between EZH2 expression and bone metastasis, indicating a higher risk of bone metastasis in patients with high EZH2 expression in primary breast cancer." (PMID 38041134, 2023). "In BRCA2-deficient breast cancer cell lines, the combination of the EZH2 inhibitor GSK126 and the PARP inhibitor rucaparib diminishes the single-agent antitumor effect of the latter." (PMID 36263120, 2022).
breast cancer (continued). "In the context of adverse outcomes, BPA exposure in human breast cancer MCF7 cells, and the mammary glands of six-week-old mice increased the expression of Enhancer of Zeste Homolog 2 (EZH2), a histone methyltransferase strongly associated with breast cancer." (PMID 35010832, 2022). "In breast cancers, EZH2 is associated with the high-grade, ER-negative status of basal-like poor prognosis." (PMID 35955891, 2022). "Recent work from our group and others has highlighted histone methyltransferase EZH2 (Enhancer of zeste homolog 2) as a promising target in BRCA1-deficient breast cancer." (PMID 35715861, 2022). "In an accompanying in vivo experiment, EZH2 inhibition was shown to improve the antitumor effect of platinum drugs in BRCA1-deficient murine mammary tumors." (PMID 36230683, 2022). "Enhancing miRNA-33a expression is associated with EZH2 down-regulation and suppression of breast cancer progression." (PMID 35236381, 2022). "Our data suggest that EZH2 inhibition can be combined with ATM inhibition to provoke toxic DSBs leading to apoptosis-mediated cell death in BRCA1-deficient breast cancer cells." (PMID 35715861, 2022). "Together, these results indicate that the synergistic cytotoxicity of combined EZH2/ATM inhibition in BRCA1-deficient mouse mammary tumor cells is mediated by apoptosis." (PMID 35715861, 2022). "While overexpression of EZH2 is linked to breast cancer, in-utero exposure to BPA is able to alter the EZH2 expression in mammary tissues." (PMID 36185256, 2022). "Some studies suggest that luminal breast cancer harboring KMT2C mutation can be treated with the EZH2 inhibitor GSK126, which mitigates dysregulated gene expression patterns and aberrant cell proliferation." (PMID 35453496, 2022). "Using the Kaplan-Meier Plotter (KM Plotter) database, we found that higher EZH2 expression was associated with poor survival outcomes for patients with breast cancer, as well as patients with breast cancer with lymph nodule metastasis." (PMID 35085106, 2022). "In order to identify synthetic lethal partners of EZH2 that are specifically effective in BRCA1-deficient breast cancer, we used BRCA1-deficient and -proficient mammary tumor cell lines to perform a high-throughput drug screen in combination with GSK126." (PMID 35715861, 2022). "It has been suggested that EZH2 enforces the silencing of E-cadherin in basal breast cancers and BRCA1-deficient tumors, and promotes the mesenchymal cell states of these carcinoma cells by driving H3K27me3 that is associated with the CDH1 promoter." (PMID 33572395, 2021). "Firstly, Chipbase database analysis exhibited a close association between SNHG1 and EZH2 levels in breast cancer tissues." (PMID 34806925, 2021). "ZMYND8 depletion not only enhances Polycomb-dependent function of EZH2 in hypoxia-exposed breast cancer cells or von Hippel–Lindau (VHL)-deficient ccRCC cells, but also suppresses the FOXM1 transcription program." (PMID 33593912, 2021). "EZH2 has been shown to be overexpressed in a number of tumours including BRCA1-deficient breast cancers." (PMID 34287743, 2021). "Overexpression of EZH2 is a predictor of poor clinical outcomes in breast cancer patients and is associated with breast cancer metastasis." (PMID 34859108, 2021). "Early studies by Kleer at al demonstrated that EZH2, a Polycomb Group (PcG) protein and transcriptional repressor involved in regulating cellular memory, was strongly associated with breast cancer aggressiveness." (PMID 34659647, 2021). "It has been shown that EZH2 is overexpressed in many tumors, such as breast cancer, ALL, Burkitt lymphomas, and is associated with poor clinical prognosis." (PMID 32512882, 2020). "Strong EZH2 expression was associated with increased tumor cell proliferation in many cancer types, including astrocytoma, breast cancer, prostate cancer, bladder cancer, hepatocellular carcinoma, colon cancer, lung cancer, and pancreatic cancer." (PMID 33330073, 2020).
breast cancer (continued). "Immunohistochemical analysis of human breast cancer specimens and flow cytometry analysis of tumor-infiltrating macrophages in mice showed a positive association of EZH2 with LOXL4 expression and macrophage infiltration." (PMID 32754259, 2020). "The genetic deletion of EZH2 reportedly resulted in the down-regulation of cyclin D1 in breast cancer and caused the up-regulation of p21 in ovarian cancer, triggering cell-cycle arrest at the G1/S phase." (PMID 33330073, 2020). "Similar findings were reported by a subsequent study of 190 breast cancer cases, with high EZH2 protein expression associated with higher histologic grade, locally advanced cancers and the presence of metastatic disease at the time of diagnosis." (PMID 33050946, 2020). "Overexpression of EZH2 has been frequently observed in breast cancer and is associated with breast cancer aggressiveness and the sensitivity to chemotherapy." (PMID 34968306, 2020). "A previous study has demonstrated that EZH2 can inhibit breast cancer susceptibility gene 1 (BRCA1) in breast cancer." (PMID 31830649, 2020). "To further study the association of identified EZH2 target genes with breast cancer, we explored the type/number of mutations observed in them in online cancer genomics data." (PMID 30760814, 2019). "This is thought to be the case in breast cancer, where EZH2 overexpression is associated with poor prognosis." (PMID 31263101, 2019). "EZH2 overexpression was linked to the transformed phenotype initially in solid tumors including prostate cancer and breast cancer." (PMID 31263101, 2019). "EZH2, which is highly expressed in breast cancer, promotes tumor progression and is associated with poorer patient outcome." (PMID 30655550, 2019). "Downregulation of EZH2 has been associated with higher expression of oestrogen receptor and increased sensitivity to tamoxifen in advanced breast cancer patients." (PMID 31088547, 2019). "This Polycomb-dependent (PcD) function of EZH2 is implicated in cancer due to its frequent overexpression in many aggressive, metastatic tumors such as prostate and breast cancer 5-9." (PMID 31410199, 2019). "Our semi-quantitative and quantitative real time data validated six direct targets of EZH2 significantly associated with the breast cancer." (PMID 30760814, 2019). "EZH2 overexpression has been associated with aggressive tumor growth in breast cancer, in endometrial carcinomas, and melanoma as well as in prostate cancer." (PMID 31317325, 2019). "Overall, the present study identifies a strong association between NIC and EZH2 particularly in the progression of breast cancer in smokers through a novel axis involving nAChR and Myc." (PMID 29396474, 2018). "All the cases were carefully selected and compared based on age of the breast cancer patients, the minimum stage of the disease based on grade and histological similarity of the tumor as EZH2 expression is associated with aggressiveness of the disease." (PMID 29396474, 2018). "EZH2 is mutated or highly expressed in many types of cancer, including lymphoma, melanoma, prostate cancer, and breast cancer." (PMID 30150556, 2018). "Combined genotypes of EZH2 rs12670401 (TC + CC) and EZH2 rs6464926 (CT + TT) were associated with breast cancer susceptibility." (PMID 29089464, 2018). "EZH2 rs12670401 and EZH2 rs6464926 polymorphisms have been proved to be in significant correlation with breast cancer susceptibility and prognosis." (PMID 29089464, 2018). "In breast cancer, EZH2 overexpression is significantly associated with the estrogen receptor-negative (ER-) subtype and worse clinical outcome." (PMID 30022044, 2018). "In breast cancer, elevated EZH2 has been linked to cell proliferation and metastasis and a poor prognosis for breast cancer patients." (PMID 30253781, 2018). "A previous study also found that high expression of EZH2 was associated with poor outcome in breast cancer." (PMID 29089464, 2018).